NOTCH3 (notch receptor 3)
Diseases named in the same sentence as NOTCH3 in open-access papers (continued):
Sharing a sentence is not in itself a finding about the gene and the disease.
breast carcinoma (continued). "To clarify the role of Notch3 in breast cancers, we first assessed Notch3 protein expression by immunohistochemistry in 21 paired infiltrating adenocarcinoma/adjacent healthy tissue." (PMID 36854682, 2023). "We then identified CpG probes in a CpG island flanking the TSS (transcription start site) of Notch3 and looked for methylation in breast cancer cell lines." (PMID 36854682, 2023). "Conversely, knockdown of Notch3 by siRNA caused significant downregulation of STAT5A and lowered levels of p-STAT5 in breast cancer cell lines." (PMID 38124049, 2023). "The purpose of the current study is to explore the regulatory mechanism of EMT and metastasis through a Notch3/STAT5A axis in breast cancer." (PMID 38124049, 2023). "As expected, enforced Notch3 expression up-regulates the expression of STAT5A in cell lines of the luminal subtype of breast cancer, whereas suppressing Notch3 expression inhibits the expression of STAT5A in triple-negative breast cancer cell lines." (PMID 38124049, 2023). "Among the cancer cells expressing Notch3, two distinct clusters of epithelial cancer cells were visible, but most of the cells were fibroblasts in every subtype of breast cancer." (PMID 36854682, 2023). "The present study demonstrates that Notch3 inhibits metastasis in breast cancer through inducing transcriptionally STAT5A, which was associated with tumor-infiltrating immune cells, providing a novel strategy to treat breast cancer." (PMID 38124049, 2023). "Regulation of p21 by Notch3 has also been proposed to act as a tumor suppressor in breast cancer by inducing senescence." (PMID 36854682, 2023). "Based on previously published datasets on Notch3 mRNA expression in breast cancer and melanoma, we confirmed that Notch3 mRNA expression was significantly decreased in all breast cancer subtypes." (PMID 36854682, 2023). "As Notch3 and STAT5A perform similar tumor-suppressive effects on EMT and metastasis of breast cancer, current study investigated the relationship between STAT5A and Notch3 and their roles in tumorigenesis and metastasis of breast cancer." (PMID 38124049, 2023). "As expected, expression of the Notch3-target gene, STAT5A, was also found to be positively associated with the period of recurrence in patients with breast cancer (p < 1E-16, HR = 0.65)." (PMID 38124049, 2023). "Among different Notch family members, Notch3 is found to maintain a luminal phenotype and suppress the tumorigenesis and metastasis of breast cancer, in part involving estrogen receptor-α (ERα) serving as a transcriptional target of Notch3." (PMID 38124049, 2023). "Altogether, these data, show that Notch3, in breast cancer cells, induces a strong expression of HeyL that leads to downregulation of Mybl2, which leads to decreased proliferation." (PMID 36854682, 2023). "As methylation of the Notch3 gene promoter has been described in breast cancer cell lines, we sought to confirm these data and expand to large published datasets." (PMID 36854682, 2023). "Forced Notch3 expression induced a dose-dependent reduction of colony formation, demonstrating a cell autonomous effect of Notch3 in limiting breast cancer progression, supporting the good prognostic impact of Notch3 expression observed in cancer cells." (PMID 36854682, 2023). "Here, we initially characterized Notch3 expression in human breast cancers using Tumor Micro Array (TMA) and observed a decrease in Notch3 expression in epithelial cancer cells associated with decreased patient survival." (PMID 36854682, 2023). "Notch3 maintains the epithelial phenotype of breast cancers through directly binding to the promoter and modifying the expression of ERα or GATA-3." (PMID 38124049, 2023). "In another study, NOTCH3 was found to inhibit EMT in breast cancer by activating downstream transcription complexes." (PMID 37239838, 2023).
breast carcinoma (continued). "Increasing evidence has shown a regulatory role for Notch3 in breast cancer, and the investigation of potential downstream targets of Notch3 will expand our understanding of the mechanism of breast cancer metastasis." (PMID 38124049, 2023). "In our preliminary experiments, the consistent expression pattern of STAT5A and Notch3 in different breast cancer cell lines was found and a CSL-binding site was predicted in the promoter region of STAT5A." (PMID 38124049, 2023). "To explore the role of Notch3 in breast cancer and its effect on EMT progression in breast cancer cells, we silenced Notch3 in MCF-7 cells using siRNA." (PMID 36139447, 2022). "We analyzed the protein levels of Notch3 and GSK3β in the pathological parameters of 68 human breast cancer samples." (PMID 36139447, 2022). "From data obtained from clinical tissue, Notch3 expression was significantly consistent with GSK3β expression in breast cancer tissue samples." (PMID 36139447, 2022). "Immunohistochemistry of Notch3 and GSK3β in breast cancer specimens revealed that Notch3 and GSK3β expression are positively associated (r = 0.416, p = 0.001)." (PMID 36139447, 2022). "In conclusion, Notch3 and GSK3β mRNA overexpression suggest a good prognosis for patients with breast cancer." (PMID 36139447, 2022). "We first performed an extensive analysis of the Breast Cancer Gene-Expression Miner v4.7 database to explore the relationship between Notch 3 and GSK3β." (PMID 36139447, 2022). "In summary, our research findings indicated that Notch3 represses the processes of EMT in breast cancer, which is consistent with our previous reports." (PMID 36139447, 2022). "Meanwhile, another study from our group showed that Notch3 can inhibit EMT in breast cancer epithelial cells by transactivating GATA3 and Kibra." (PMID 36139447, 2022). "At the same time, Notch3 has the opposite effect on EMT through the transactivation of Hippo/Yap signaling in breast cancer." (PMID 35954450, 2022). "In the present study, we employed a functionalized AuNPs system for the delivery of miR-206 mimic and demonstrated that miRNA when delivered through gold nanoparticles is effective in treating Luminal A type of breast cancer by targeting the NOTCH 3 gene." (PMID 35304514, 2022). "Upregulation of NOTCH1 and NOTCH3 (perhaps) in basal- like breast cancer cell(BLBCC) leads to secretion of cytokines, such as IL1β and CCL2, which recruit monocytes that mature into tumor-associated macrophages (TAMs) in stroma." (PMID 36517618, 2022). "PF-06650808 is a novel anti-NOTCH3 ADC that has achieved remission with a controlled safety profile in breast cancer patients with positive NOTCH3 expression." (PMID 36517618, 2022). "Another study showed that IL-6R antagonist Tocilizumab significantly decreases breast cancer stem cell and inhibits tumor growth in Notch3-expressing breast cancers." (PMID 35924148, 2022). "Our previous studies showed that estrogen receptor (ER)α inhibits EMT by suppressing Bmi1, and Notch3 transcriptionally upregulates ERα in breast cancer." (PMID 36139447, 2022). "We initially evaluated the effects of recombined Notch3 and GSK3β expression on breast cancer cell invasion using migration and invasion assays." (PMID 36139447, 2022). "In this study, we revealed that Notch3 was an essential antagonist of EMT in breast cancer cells by transcriptionally upregulating GSK3β." (PMID 36139447, 2022). "One NOTCH3 antibody–drug conjugate (PF-06650808) benefited patients with NOTCH3-positive breast cancer tumors." (PMID 35229725, 2022). "Of the 162 patients, the Notch3 positivity rate was significantly higher in ER+ (112/162; 69.1%) than ER− (50/162; 30.9%) breast cancer (P = 0.020)." (PMID 34006834, 2021). "Recent studies have also shown that Notch3 plays an anti-oncogene role in breast cancer development and inhibits tumor growth." (PMID 34006834, 2021).
breast carcinoma (continued). "The p66Shc/NOTCH3 interplay modulates self-renewal and hypoxia survival in breast cancer stem/progenitor cells." (PMID 34374886, 2021). "All these data support our observations that in luminal A breast cancer cells, NOTCH3 can act as an oncogenic protein when it is phosphorylated at serine 1672, whereas the nonphosphorylated form of N3ICD remains tumor-suppressive." (PMID 33775697, 2021). "NOTCH3 can promote tumor cell self-renewal and aggressive tumor behavior; thus, targeting NOTCH3 to prevent breast cancer metastasis is clinically efficacious in breast cancer patients." (PMID 34374886, 2021). "In particular, Notch3 expression was elevated 1.741-fold in breast cancer compared to normal tissue (P = 3.75E-4), and PTEN was elevated 1.702-fold (P = 0.007)." (PMID 34006834, 2021). "show that NOTCH3 activation suppresses the EMT of breast cancer, leading to inhibition of lung metastasis." (PMID 34374886, 2021). "Our results revealed that Notch3-mediated activation of PTEN inhibited breast cancer cell proliferation, migration/invasion, and tumorigenesis by transcriptional activation of PTEN." (PMID 34006834, 2021). "For example, PF-06650808 is a novel anti-Notch3-auristatin conjugate that has demonstrated manageable toxicity and signs of anti-tumour activity in breast cancer patients." (PMID 34295896, 2021). "have shown that NOTCH3 is involved in regulation of IL6-mediated hormone therapy resistance in breast cancer." (PMID 34374886, 2021). "Circ_NOTCH3 served as a proto-oncogene in basal-like breast carcinoma by sponging miR-205-5p, and circPVT1 improved the malignant development of osteosarcoma through the sponge mechanism of miR-205-5p." (PMID 34174955, 2021). "The correlation between NOTCH3 and PD‐L1 expression in breast cancer, and especially in breast cancer stem cells, is a good illustration of this." (PMID 34542930, 2021). "In the nucleus, the CBFB-RUNX1 transcriptional complex represses NOTCH3, an oncogene in breast cancer." (PMID 33945523, 2021). "After restricting the analysis to intrinsic molecular breast cancer subtypes, we found that high Notch3 expression had a better prognosis for those with the luminal A, luminal B subtype compared to those with low Notch3 expression." (PMID 34006834, 2021). "MK-0752 (25 μM) and RO4929097(10 μM), alone or in combination with tocilizumab, suppressed tumor growth, but enhanced the CSCs in breast cancer cells expressing Notch3, while inducing IL-6." (PMID 33673088, 2021). "In general, we have identified a positive correlation between Notch3 and PTEN in breast cancer and confirmed a role for the Notch3-PTEN axis in inhibiting tumor proliferation and migration/invasion." (PMID 34006834, 2021). "At the same time, we also report that Notch3 knockdown can inhibit the proliferation and the migration of 4T1 murine mammary carcinoma cells via the CCL2/CCR4 axis." (PMID 33244467, 2020). "Gamma-secretase cleaved activated Notch1 and Notch3 proteins have been detected in majority of breast cancer cell lines." (PMID 32211044, 2020). "Using the model of human mammospheres, Sansone and collaborators revealed IL-6-induced Notch-3-dependent up-regulation of CAIX promoting the malignancy in breast cancer stem cells." (PMID 32707920, 2020). "Immunohistochemistry results revealed that in patients with breast cancer, the expression of Notch3 and were negatively correlated with the FSCN1 levels significantly." (PMID 33099573, 2020). "We present in vitro and in vivo evidence and the molecular mechanism by which Notch3 plays an important role in promoting mammary gland development and suppressing breast cancer cell growth, invasion, and migration." (PMID 33244467, 2020). "The crosstalk between stromal and breast cancer cells signaling pathways converge as STAT1 promotes transcriptional responses to NOTCH3." (PMID 33680952, 2020).
breast carcinoma (continued). "In the future, we will further explore the mechanism of other targets of lncRNA SNHG3, and explore the role of Notch 1 and Notch 3 in breast cancer." (PMID 32883233, 2020). "In this study, we investigated the influence of Notch3 on mammary gland development by using Notch3 knockout mice as well as the effect of Notch3 on the biology behaviors of the murine breast cancer cell 4T1 by overexpressing or knocking down Notch3." (PMID 33244467, 2020). "This multi-signaling pathway uses both paracrine antiviral and juxtacrine neurogenic locus notch homolog protein 3 (NOTCH3) signaling to enhance breast cancer survival and therapy resistance." (PMID 33680952, 2020). "It should be noted, however, that contrary reports of the role of Notch3 in breast cancer have also been published." (PMID 32210034, 2020). "Pregnant mice expressing higher levels of an activated intracellular form of NOTCH3 develop luminal mammary tumors resembling IBC that frequently metastasize." (PMID 31854063, 2020). "Our group has focused on the effect of Notch family molecules on the proliferation, EMT, invasion and metastasis of breast cancer cells, and we have found that Notch3 can be a tumor suppressor that inhibits EMT in MDA-MB-231 cells." (PMID 31096822, 2019). "In this view, a novel anti-Notch3 antibody-drug conjugate currently named PF-066580808 is now under clinical investigation (phase I) for the treatment of breast cancer, including TNBCs." (PMID 31379945, 2019). "In fact, it was observed that STAT3-dependent upregulation of Notch-3, Jagged-1, and carbonic anhydrase IX correlates with growth and invasion of breast cancer cells to bone." (PMID 31847214, 2019). "Using human breast tumor microarray, we found that CBFB and RUNX1 levels were significantly lower in breast cancer tissues compared to normal breast tissues while NOTCH3 levels were the opposite." (PMID 31061501, 2019). "Across other cancer cell lines tested here, brivanib-induced apoptosis of CCA cells and breast cancer cells subsequently to Notch3 silencing." (PMID 30765875, 2019). "Notch3 inhibits epithelial-mesenchymal transition by activating Kibra-mediated Hippo/YAP signaling in breast cancer epithelial cells." (PMID 31049030, 2019). "Previously, we found that overexpression of the intracellular domain of Notch3 (N3ICD) can inhibit EMT in breast cancer cells." (PMID 31096822, 2019). "For example, we will also test the permeability of breast cancer cell TJs by trans-epithelial resistance measurements (TER) in the conditions of Notch3 overexpression or knockdown." (PMID 31096822, 2019). "A significant decrease in Notch3 was observed in primary breast cancer, compared with normal tissue, suggesting a protective mechanism against Notch3-initiated cellular senescence." (PMID 30515368, 2018). "As reported, the CCR2 protein of monocytes can promote breast cancer metastasis through the Notch 3 pathway." (PMID 30381359, 2018). "In the present study, we report that Notch3 expression positively correlates with that of GATA-3, and both are associated with estrogen receptor-α (ERα) expression in breast cancer cells." (PMID 30100605, 2018). "Our earlier study has revealed that Notch3 maintained luminal phenotype and suppresses tumor metastasis in breast cancer." (PMID 30109262, 2018). "Using tumor xenograft models, we demonstrate herein that Notch3 restrains metastasis of breast cancer in vivo via regulation of GATA-3." (PMID 30100605, 2018).
breast carcinoma (continued). "Our investigation of the regulatory mechanism of Notch3 and GATA-3 found that both were positively associated with ER expression in breast cancers." (PMID 30100605, 2018). "Stromal cells including fibroblasts have also been shown to promote therapy resistance in breast cancer cells through expression of Jagged1 and exosomal transfer leading to Notch3 and STAT1 signaling in cancer cells." (PMID 30515368, 2018). "Notch3 thus, indirectly, plays an important role in endocrine resistance observed in metastatic breast cancer by influencing stem cell behavior." (PMID 30515368, 2018). "Taken together, our results elucidated that miR-221/222 promote EMT via targeting Notch3 in breast cancer cell lines suggesting that miR-221/222 can serve as a potential therapeutic target in BLBC." (PMID 30109262, 2018). "On the contrary, expression of GFP-AURKA in vMCF-7Raf-1 1GXCRISPR-NOTCH3 cells failed to restore their invasive ability, demonstrating that NOTCH3 expression is required to mediate AURKA-induced breast cancer cells’ aggressiveness." (PMID 30180881, 2018). "Collectively, our results suggest that GATA-3 expression is positively regulated by Notch3 in breast cancer cells." (PMID 30100605, 2018). "The data presented in this study highlight a mechanism by which miR-221/222 promote migration and invasion by targeting Notch3 in breast cancer cell lines." (PMID 30109262, 2018). "This was also observed in endocrine resistant luminal breast cancers whereby blockage of Notch3 abrogated the growth of these ER-resistant cells." (PMID 30515368, 2018). "Notch3 is known to be overexpressed in luminal breast cancer cells and inhibits epithelial to mesenchymal transition (EMT)." (PMID 30109262, 2018). "This notion was further confirmed by the observation that Notch3 was significantly inhibited in ERα-positive breast cancer cells treated with miR-221/222 mimics in a dose-dependent manner." (PMID 30109262, 2018). "We next assess influence of Notch3 knockdown on the motility breast cancer cell via wound healing assay." (PMID 30100605, 2018). "Here, we report that miR-221/222 expression is inversely correlated with Notch3 expression in breast cancer cell lines." (PMID 30109262, 2018). "NOTCH3 expression was required to induce in vitro self-renewal capacity and a CD44high/CD24low breast cancer stemlike phenotype in vMCF-7∆Raf1 1GX cells." (PMID 30180881, 2018). "In this study, we uncovered the linkage between NOTCH3 expression and development of distant metastases in experimental breast cancer models." (PMID 30180881, 2018). "To confirm in a different breast cancer model the finding that NOTCH3 expression is restricted to metastatic cells, we used CD44high/CD24low MDA-MB-231 TNBC cells isolated from experimental lung metastases (MDA-MB-231 LM)." (PMID 30180881, 2018). "In breast cancer patients, high GATA-3 expression is associated with higher Notch3 expression and lower lymph node metastasis, especially for hormone receptor (HR) positive cancers." (PMID 30100605, 2018). "To explore the possible regulation between these two genes, we silenced or overexpressed Notch3 or GATA-3 in breast cancer cells." (PMID 30100605, 2018). "Abrogation of NOTCH3 expression significantly reduced the self-renewal and invasive capacity of ex vivo breast cancer cells, restoring a luminal CD44low/CD24high/ERαhigh phenotype." (PMID 30180881, 2018). "And, finally, exosomal RNA produced by stromal cells were shown to activate RIG-I anti-viral signaling in breast cancer cells, leading to the expansion of therapy resistant breast cancer cells in a mechanism involving NOTCH3 induction." (PMID 29515996, 2018). "In the present study, we found that bakuchiol repressed Notch 3 expression, possibly exerting an inhibitory effect on the self-renewal capacity of BCSCs and metastasis of breast cancer cells." (PMID 29093680, 2017).